STAT3 (signal transducer and activator of transcription 3)
Diseases named in the same sentence as STAT3 in open-access papers (continued):
Sharing a sentence is not in itself a finding about the gene and the disease.
colitis (continued). "The IL-10 cytokine family has been shown to facilitate the gut antimicrobial defense and promote mucosal barrier integrity and repair by activating STAT3, while IL-17, TNF-α, and IFN-γ induce colitis by disrupting the mucosal barrier function of the immune system." (PMID 32670220, 2020). "Notably, administration of uvaol significantly decreased the phosphorylation of STAT3 and ERK in colon tissues of DSS-induced colitis mice and LPS challenged macrophages." (PMID 32411289, 2020). "In the TNBS mouse model of colitis, berberine reduces IFNγ, IL-1α, IL-6, IL-17, and TNFα expression in colonic tissues and sera and suppresses Th1 and Th17 cells through reduction of STAT1, STAT3, and NF-κB phosphorylation." (PMID 32855621, 2020). "Naringin (4′,5,7-trihydroxyavanone-7-rhamnoglucoside), a major flavanone glycoside that occurs naturally in citrus fruits, inhibits the severity of colitis and CRC development through regulation of the MDSCs’ immunosuppressive function via the NF-κB/IL-6/STAT3 axis in colorectal tissues." (PMID 33384962, 2020). "EEP exhibits protective and anti-colitis effects in DSS-induced mice model and anti-inflammatory properties in LPS-induced RAW 264.7 macrophage cells by suppressing phosphorylation of NF-κB and STAT3." (PMID 30621304, 2019). "After combining this evidence, we hypothesized that TRYP exerted its protecting effect against DSS induced colitis via regulating the TNF-α/NF-κB and IL-6/STAT3 signaling pathways." (PMID 29724065, 2018). "ETBF triggers colitis and strongly induces colonic tumors in multiple intestinal neoplasia (MIN) by Stat3 activation with colitis characterized by a selective T helper type 17 (Th17) response distributed between CD4+ T cell receptor-α/ β (TCR α/ β)+ and CD4/8-TCRγ/ δ+ T cells." (PMID 29707157, 2018). "Besides, the phosphorylation level of STAT3 was decreased after administration of TRYP, indicating the protective effect of TRYP on colitis was closely related with STAT3." (PMID 29724065, 2018). "Accordingly, in a previous study in animals with DSS-induced colitis, Hiller and colleagues found that GPX2 was induced through activation of STAT3, a transcription factor involved in wound healing, proliferation, and protection from apoptosis during acute injury." (PMID 29881384, 2018). "IL-6 plays important roles in tumor initiation via PLCγ1–mediated inflammatory response in colitis environment, and also after recovered colitis by removal of DSS, crosstalk between stat-3 and PLCγ1 is involved in tumor progression and development through apoptosis and proliferation." (PMID 29464031, 2018). "In the intestinal epithelium, deficiencies in STAT1, STAT3, or STAT5A did not lead to spontaneous inflammation, even though these mice were prone to chemical‐induced colitis." (PMID 29941542, 2018). "In our study, phosphorylation of the STAT3 Tyr705 in particular was associated with colitis of DSS-induced mice, but not STAT3 Ser727." (PMID 28383063, 2017). "Furthermore, mucosal T-cells activated by STAT3 contribute to the progression and perpetuation of DSS induced colitis." (PMID 27258062, 2016). "Additionally, mTOR and STAT3 pathways and their crosstalk are significantly upregulated in patients with IBD and inhibition of mTOR ameliorated DSS-induced colitis." (PMID 27144580, 2016). "To investigate whether inhibition of colitis in gp130757F/F miceis due to altered gp130 signalling, we examined activation of signallingmolecules STAT1, STAT3, ERK1/2 and NfκB in the colon of DSS-treatedand untreated gp130757F/F and WT mice." (PMID 26848037, 2016). "Recent studied have revealed dextran sulfate sodium-induced colitis was mild in mice lacking STAT3 in macrophages and gut epithelial cells." (PMID 24451125, 2013). "Moreover, the role of STAT3 in IBD has been documented by human IBD studies and animal models of colitis." (PMID 24451125, 2013).
colitis (continued). "In contrast to our findings, STAT3 activation was reported to promote colitis and prevent wound healing, but this study does not discriminate in which cell-type STAT3 is hyperactivated." (PMID 22675454, 2012). "It was shown that increased O-linked N-acetylglucosamine modification (O-GlcNAcylation) of STAT3 upregulated the expression of proinflammatory cytokines such as IL-6, IL-1β, and TNF-α, while downregulating the level of the anti-inflammatory cytokine IL-10 and aggravating colitis in mice." (PMID 40078988, 2025). "We hypothesized that the selective inhibition of STAT3 by HCB-5300 and HCB-5400 would mitigate colonic injury, suppress pro-inflammatory cytokine expression (e.g., IL-6), and improve histopathological outcomes in DSS-induced colitis." (PMID 41465408, 2025). "Butein, a major constituent of Toxicodendron vernicifluum ameliorated colitis in IL-10(-/-) mice by reducing the colonic inflammatory score by > 50%, reducing the expression levels of IL-6, IL-1β, IFN-γ pSTAT3 and MMP-9, also inhibiting IL-6-induced activation of STAT3 in Colo 205 cells." (PMID 39494333, 2024). "Furthermore, MLKL attenuated colon inflammation and colitis tumorigenesis via suppression of inflammatory responses, inhibited intestinal tumorigenesis by suppressing the IL-6/JAK2/STAT3 pathway and promoted cellular differentiation in myeloid leukemia by facilitating the release of G-CSF." (PMID 36828808, 2023). "After observing aberrant p-STAT3 staining in colonic epithelial cells of TAM-treated Klf5ΔIND mice and DOX-treated C2BBEΔIND cells after IL-22 stimulation, we next investigated whether such a phenomenon is present in patients with colitis." (PMID 35393949, 2022). "Using a novel humanized model of experimental colitis, we demonstrate that TNF interfered with the tissue repair program via induction of a soluble natural antagonist of IL-22 (IL-22Ra2; IL-22BP) in the colon and abrogated IL-22/STAT3-mediated mucosal repair during colitis." (PMID 35383266, 2022). "The ratio of Ly5.1+/Ly5.1– cells recovered in the MLN of treated mice was significantly higher in mice treated with STAT3 GOF Tregs compared with those treated with WT Tregs (14.9 versus 3.6, respectively), suggesting that local control of colitis cell accumulation may be impaired in these mice." (PMID 36136607, 2022). "The obtained results indicated that both AG490 and arbutin could alleviate colitis symptoms, downregulate inflammatory indexes, and inhibit the phosphorylation of JAK2 and STAT3 in a mouse colitis model as well as in LPS-induced epithelial and immune cell inflammation models." (PMID 34594215, 2021). "Similar results were obtained for mice with TNBS-induced colitis, and an investigation into the mechanism of the anti-inflammatory and anti-oxidant effects led to the possible explanation that PCA modulates SphK/S1P signaling, which serves as an important pathway for activation of STAT3 and NF-κB." (PMID 34073220, 2021). "Likewise, TRYP was found to be effective in protecting mice against experimentally-induced colitis via regulation of the tumor necrosis factor (TNF)/nuclear factor (NF)-κB and interleukin (IL)-6/signal transducer and activator of transcription 3 (STAT3) signaling pathways." (PMID 32792961, 2020). "The results demonstrated that IFN-γ treatment could enhance the capacity of exosomes derived from MSCs to attenuate mice colitis phenotype via upregulating the level of miR-125a and miR-125b, which directly targeting on the 3′-UTR of Stat3 to repress Th17 cells and the inflammation." (PMID 32733020, 2020). "Importantly, when STAT3 blocker was added, cytokine secretion from the macrophages in experimental colitis was not decreased by CST." (PMID 32110996, 2020). "Colitis rats exhibited a remarkable tendency to up-regulate the target proteins (P < 0.05, P < 0.01), while CP could notably lower the levels of pp65, TLR4, p-STAT3, and p-JAK2 (P < 0.05, P < 0.01, P < 0.001)." (PMID 30042683, 2018).
colitis (continued). "Takentogether, altered total colonic STAT3 activation does not account for resistanceto acute DSS-induced colitis in gp130757F/F mice, but the alteredsusceptibility may be due to the STAT3 activation in myeloid cells." (PMID 26848037, 2016). "Because of the crucial role of STAT3 in the expansion of myeloid-derivedsuppressor cells, we then analyzed the influence of altered gp130/STAT3signalling on the frequency, phenotype and functional properties of myeloid cellpopulations during DSS-induced colitis." (PMID 26848037, 2016). "The proliferative and survival effects of IL-6 on IEC are largely mediated by the transcription factor Stat3 as mice lacking Stat3 in colonic epithelium develop fewer adenomas in spite of the fact that they have more severe colitis following exposure to AOM-DSS." (PMID 20885960, 2010). "However, currently, no studies on the regulation of STAT3 expression by USP25 in colitis exist." (PMID 39773987, 2025). "Thus, IL-6/STAT-3 signaling could contribute to FOLFIRI-related mucosal damage by controlling the proliferation and survival of intestinal epithelial cells as observed in colitis." (PMID 29706892, 2018). "In conclusion, our work revealed decreased retention of Cys A in the PBMC of a TNBS-induced colitis animal model and suggested the possible mechanism that chronically elevated inflammation in blood could induce P-gp up-regulation in PBMC through the STAT3/Nf-κb pathway." (PMID 26324318, 2015). "Additionally, studies in genetically engineered mice have demonstrated that epithelial STAT3 activation in dextran sodium sulfate colitis is dependent upon IL-22 rather than IL-6, and that both IL-22 and epithelial STAT3 is important in wound-healing experiments in vivo." (PMID 23379788, 2013). "We also recognize a limitation that the mechanisms of NF-κB and STAT3 on regulating the SLC7A11/GSH/GPX4 antioxidant axis and XJS targeting FGL1 to inhibit colitis are not verified in vitro, which will be conducted in a future study." (PMID 37153794, 2023). "Our study demonstrated correlations between miR-155, SOCS1, and STAT3 in the ascending colon of PSC patients, with or without concurrent colitis, and in the sigmoid colon of UC patients." (PMID 35563301, 2022). "Phosphorylation of STAT3 at Tyr705, not Ser727 in the DSS-colitis model correlates with previous studies." (PMID 28383063, 2017). "Based on our experiments, we presumed that, unlike classical IL-6-induced STAT3 activation, type I IFN-induced STAT3 might not play a protective role in DSS-induced colitis." (PMID 34349238, 2021). "Collectively, our data suggest that PKA activation is an early event in experimental colitis, and the disassociated PRKAR2A after PKA activation might take part in the subsequent STAT3 activation, but it is not dependent on the classical IL-6 signaling." (PMID 34349238, 2021). "Given that knockdown of Stat3 does not have an effect on Stat1 expression in shStat3 mice and the similar disease phenotype in GP130∆STAT/+ and shStat3 mice after DSS treatment, these further support that STAT3, but not STAT1, confers protection against colitis." (PMID 33673239, 2021).
Obesity (359 papers, 2011 to 2026). Accumulation of substantial excess body fat. "Our findings indicate an opposing role of Stat3 in regulating M1/M2 in obesity-associated diabetes vs. in the tumor microenvironment." (PMID 40801626, 2025). "Myeloid cells respond to IL-6 through Jak/Stat3, which has been implicated in inflammatory disease and inflammation-promoted obesity-associated cancer." (PMID 40801626, 2025). "Our data provides evidence that ablating Jak2 or Stat3 in myeloid cells reverses the phenotype of obesity/ATM inflammation-linked insulin resistance in vivo." (PMID 40801626, 2025). "Another hepatokine we found elevated in the OBO group was Fetuin B, which is modulated through leptin–STAT3 signaling and is known to exhibit an association with leptin in the context of obesity." (PMID 40076884, 2025). "Predominantly, these signaling pathways include PI3K/Akt, Ras/MAPK, and STAT3 signaling pathways, which are impacted by the cancer risk factors associated with obesity." (PMID 37954072, 2023). "The activation of IL-6/JAK/STAT3 signaling in the liver promotes the development of obesity-associated HCC through exacerbating metabolic stress-induced inflammation and immune response." (PMID 37361533, 2023). "Obesity-induced cancer progression is associated with dysregulated inflammation which is mediated by STAT3." (PMID 35062950, 2022). "A mice study showed that obesity is linked to altered metabolism in colon carcinogenesis through the JNK/STAT3-signaling pathway." (PMID 35967794, 2022). "Risk factors such as a high-fat diet and obesity have been shown to have a significant impact on STAT3 activation." (PMID 36230984, 2022). "The loss of STAT3 in T cells reduces Th17 and regulatory T (Treg) cell populations in mouse models of obesity." (PMID 33467683, 2021). "The same effect was observed when a S1P agonist (SEW2871) was administered; mice had an induced anorexigenic effect, preventing obesity and associated metabolic diseases in a STAT3/POMC-dependent axis." (PMID 34069652, 2021). "Genetic STAT3 null or STAT3 phosphorylation deficiency in hypothalamus causes central leptin resistant and severe obesity animal." (PMID 33849593, 2021). "Other than spontaneous mutations, mice were genetically engineered to develop obesity by disrupting STAT3 function." (PMID 33572982, 2021). "Their variants affect the obesity risk by modulating the binding affinity of obesity-related transcription factors, such as STAT3, CEBPB, TCF7L2, FTO, and GATA2, and changing the phosphorylation of proteins, such as BDNF with the rs6265 risk allele." (PMID 34836030, 2021). "Circulating miR-122 is upregulated during obesity/diabetes, patients at risk of CVDs have a higher circulating miR-12227–31, and miR-122 can regulate Stat3 activation which is a known repressor of miR-204 expression." (PMID 32572127, 2020). "In detail, an IL-6/Stat3-dependent formation on these NK cells seems to account to obesity-associated pathologies." (PMID 32231659, 2020). "On the contrary, the STAT3 signaling pathway has been shown to link obesity, inflammation, and cancer, suggesting a target for the treatment of obesity-associated pathologies." (PMID 32024285, 2020). "Jak2 activation has been shown to be the primary pathway by which the LepR functions on the neuroendocrine system and STAT3 signaling has been implicated in promoting obesity-mediated cancer progression." (PMID 33019728, 2020). "FNDC5 attenuates obesity-induced cardiac hypertrophy by inactivating JAK2/STAT3 associated-cardiac inflammation and oxidative stress." (PMID 30940158, 2019). "Taken together, these results highlight the crucial role of STAT3 signaling in obesity-associated HCC development and progression." (PMID 30591653, 2018). "Hyperphagia, obesity and defective locomotion were observed in mice with deficiency of LepR or its key signaling molecule STAT3 in the LH or VTA on chow diet." (PMID 28560316, 2017).
Obesity (continued). "Previously, we reported that obesity-induced increases in leptin release cause activation of the STAT3 pathway and result in hepatic expression of CD1417." (PMID 26911834, 2016). "In terms of a potential causal role of leptin as a driver of breast carcinogenesis, preclinical data show that leptin regulates JAK2/STAT3 and inflammatory cytokine related signaling, which is altered by obesity and reregulated via weight loss." (PMID 26132992, 2015). "We identified two single nucleotide polymorphisms of STAT3 associated with obesity or plasma triglyceride in a Chinese Han population." (PMID 25014397, 2014). "Our study also support that polymorphisms of STAT3 are associated with risk of obesity, but the protective effect of our investigated SNP rs1053005 is contrary to the findings by Catherine." (PMID 25014397, 2014). "Experiments using knockout mouse model showed that the disruption of neural STAT3 causes apparent leptin-resistant conditions such as obesity, diabetes and thermal dysregulation." (PMID 25014397, 2014). "In this study, we explored the association between STAT3 polymorphisms with obesity and other metabolic disorder related phenotypes in a Chinese Han population." (PMID 25014397, 2014). "There are hitherto four published reports investigating the association of STAT3 polymorphisms with obesity and metabolic disorders, but the observations are inconsistent with each other." (PMID 25014397, 2014). "We conclude that GSPE diverted differentiation of CD4+ T cells toward a Treg phenotype in murine model of obesity-associated autoimmune arthritis through a modulation of STAT3 proteins." (PMID 24223854, 2013). "This corroborates existing literature asserting STAT3’s contribution towards migratory capabilities amongst tumor cells, affirming its significance concerning progressions related specifically to obesity-associated breast malignancies." (PMID 41562922, 2026). "Moreover, selective STAT3 deletion in LepRb-expressing neurons induces hyperphagia and obesity, mirroring the phenotypes of LepRb Tyr1138 deficiency." (PMID 41251447, 2025). "Jak2 or Stat3 may therefore represent potential therapeutic targets for improving obesity-linked insulin resistance." (PMID 40801626, 2025). "Chronic activation of these neurons caused massive obesity, and importantly, the observed obesity is associated with normal p-STAT3-mediated leptin signaling but resistant to leptin treatment, highlighting a dissociation between cellular leptin sensitivity and phenotypic leptin resistance." (PMID 40540394, 2025). "Notably, it has been reported that the motivation of STAT3 signaling is linked to modulating gut microbiota in the diet-induced obesity model." (PMID 37114045, 2023). "In addition, LCN2 acts as a key mediator of HSC activation in leptin-deficient obesity via α-SMA/MMP9/STAT3 signaling, further exacerbating NASH." (PMID 37784089, 2023). "Therefore, our study identifies leptin-STAT3 as an upstream signalling pathway that activates Fetuin B and provides new insights into the pathogenic mechanisms of obesity-related metabolic disorders." (PMID 35896788, 2022). "In conclusion, the bidirectional interaction between STAT3 and the miRNAs miR-31 and miR-215 may be an important pathway through which obesity increases CRC risk." (PMID 34716428, 2022). "Moreover, conditional inactivation of IL-6Rα or STAT3 in NK cells limits obesity-associated induction by NK cells, protecting from obesity, insulin resistance, and obesity-associated inflammation." (PMID 35095876, 2021). "These key findings suggest that targeting STAT1 and STAT3 signaling could be a therapeutic target for treating the inflammatory phenotype associated with senescence in obesity-driven T2DM." (PMID 33672392, 2021). "STAT3 mutated mice, named s/s mice, develop obesity as efficiently as spontaneous mutated models." (PMID 33572982, 2021).